CD79B (CD79b molecule)
Diseases named in the same sentence as CD79B in open-access papers (continued):
Sharing a sentence is not in itself a finding about the gene and the disease.
cancer (continued). "In these specific intergroup DE genes, BCL11A, VPREB3, CD79B, CHRNA7, and SWAP70 that all involved in B cell proliferation and activation, would likely impact B cell function in MDV pathogenesis and malignant tumor formation." (PMID 30922224, 2019). "Of the ‘Cancer census genes’ most frequently involved in a copy number gain, four were in common with those in the TCGA-data (i.e. FCGR2B, TERT, CD79B and PRKAR1A)." (PMID 29371938, 2017). "Inspection of the analyzed gene set revealed that, among the ten most specific immune response cancer genes, five were bound to or an integral part of the plasma membrane (CD70, HLA-B, TNF, TNFRSF14, and CD79B)." (PMID 26856619, 2016). "In this study, we found that the human epithelial cancer cells expressed two forms of IgM (membrane bound and secreted) as well as CD79A and CD79B." (PMID 23251529, 2012). "Polatuzumab vedotin is a CD79b-targeted antibody-drug conjugate (ADC) that preferentially delivers a potent anti-mitotic agent, monomethyl auristatin E (MMAE), to B cells, which results in anti-cancer activity against B-cell malignancies." (PMID 37063860, 2023). "Genes related to B and T cell maturation (e.g. CD37, CD79B, JCHAIN, IGLL1, VPREB3, CD52), ribosomal protein genes (RPS-*, RPL-*) and cancer/stress genes (e.g. PRAME, ARHGDIB, FOS, JUN) were within the most significantly deregulated genes between clusters in those samples." (PMID 32415257, 2020). "Moreover, both sample sets shared four genes in their ‘top 20’ list of ‘Cancer census genes’ most frequently involved in a copy number gain (i.e. TERT, FCGR2B, CD79B and PRKAR1A)." (PMID 29371938, 2017). "Hence, combined with the results of PRECOG and survival analysis, it implied that the high expressions of CD20, CD22, CD79B, and ADAM28 might predict a positive response to anti-PD-1 immunotherapy for pan-cancer patients." (PMID 35634306, 2022).
infection (7 papers, 2016 to 2026). The state of being infected such as from the introduction of a foreign agent such as serum, vaccine, antigenic substance or organism. "It has been shown that there is a prolific B cell response to MAP early in the infection that wanes over time, resulting in weaker responses to mitogens, possibly due to the reduction in the expression of CD79b." (PMID 27093613, 2016). "Correlations were also found between Cd19 (R = 0.9134), Cd79a (R = 0.9865), Cd79b (R = 0.9620) and the apoptotic protein Bik, which may be involved in the B cell depletion during infection." (PMID 36400767, 2022). "On the other hand, 24 genes were significantly upregulated by infection in the R line of the HSF flock, such as CD19, CD22, CD79B, two complement-related genes CFI and CR2 (complement C3d receptor 2), FGG, and FGA (fibrinogen alpha chain)." (PMID 30678719, 2019).
blood cancer (1 paper, 2022). "Polatuzumab vedotin-piiq (Polivy®) against CD79b with an enzymatically cleavable linker, approved for blood cancer in 2019, entered cells and released a potent cytotoxic agent, MMAE, into the cytoplasm after lysosomal escape via passive diffusion." (PMID 36546903, 2022).
hematological cancers (1 paper, 2025). "As these genes were associated with other hematological and non-hematological cancers, further research is required to assess their oncogenic relevance in the CD79B-mutated group." (PMID 41295250, 2025).
CD79B also shares sentences with these, for which no sentence is quoted: primary immunodeficiency (3 papers); acute myeloid leukemia (2); breast carcinoma (2); gastric cancer (2); glioblastoma (2); glioma (2); adrenal cancers (1); Chlamydia infection (1); Cirrhosis (1); demyelinating disease (1); emphysema (1); hairy cell leukemia (1); hematological malignancies (1); herpesvirus infection (1); immune disease (1); inflammatory bowel disease (1); ischemic stroke (1); liver cancer (1); lymph node metastasis (1); Lymphadenopathy (1); metastasis (1); myelodysplastic syndrome (1); neutropenia (1); rheumatoid arthritis (1).